MMP9 (matrix metallopeptidase 9)
Diseases named in the same sentence as MMP9 in open-access papers (continued):
Sharing a sentence is not in itself a finding about the gene and the disease.
Hydrocephalus (8 papers, 2016 to 2025). Hydrocephalus is an active distension of the ventricular system of the brain resulting from inadequate passage of CSF from its point of production within the cerebral ventricles to its point of absorption into the systemic circulation. "Serum NLRP3, MMP‐9 and IFN‐γ levels and serum NLRP3 and MMP‐9 levels were independent risk factors influencing postoperative intracranial infection and postoperative hydrocephalus, respectively." (PMID 38643470, 2024). "Similar to our findings, MMP‐9 expression in the cerebral tissues and CSF is increased in hydrocephalus, indicating that MMP‐9 may be implicated in hydrocephalus after kaolin induction." (PMID 38643470, 2024). "Besides, MMP‐9 had a high diagnostic efficacy for postoperative intracranial infections and hydrocephalus in patients, which was also an independent risk factor influencing patients’ postoperative hydrocephalus and intracranial infection." (PMID 38643470, 2024). "Another study investigated the relationship between MMP-9 and hydrocephalus in patients who underwent craniotomy for severe craniocerebral trauma." (PMID 40722587, 2025). "Other research focuses on pharmacological agents that modulate genes and protein expression, such as inhibitors of matrix metallo-proteinases like MMP-9, which reduce periventricular tissue damage and improve hydrocephalus symptoms." (PMID 39908266, 2025). "The researchers found that the serum levels of MMP-9 were significantly elevated in patients with postoperative hydrocephalus compared to control subjects." (PMID 40722587, 2025). "Overall, serum NLRP3, MMP‐9 and IFN‐γ levels had high diagnostic efficacy for postoperative intracranial infection and hydrocephalus in patients." (PMID 38643470, 2024). "Subsequently, we evaluated the diagnostic efficacy of serum NLRP3, MMP‐9 and IFN‐γ levels for postoperative intracranial infection and hydrocephalus in patients by the ROC curve analysis." (PMID 38643470, 2024). "In light of this, our findings revealed that serum MMP‐9 levels were significantly elevated in post‐craniotomy patients with hydrocephalus and intracranial infections." (PMID 38643470, 2024). "Serum NLRP3, MMP‐9 and IFN‐γ levels had high diagnostic efficacy in patients with postoperative intracranial infection and hydrocephalus, among which serum NLRP3 level played a major role." (PMID 38643470, 2024). "Serum levels of NLRP3, MMP‐9 and IFN‐γ were determined using ELISA kits, with their diagnostic efficacy on intracranial infections and hydrocephalus evaluated by receiver operating characteristic curve analysis." (PMID 38643470, 2024). "In conclusion, USSCs exerted anti-inflammatory effects by suppressing both TGF-β specific isoforms, CTGF and MMP-9, recovered IL-10, restored aquaporins expression towards baseline, and reduced hydrocephalus." (PMID 33897371, 2021). "In the Tgfb1 overexpression model, the changes of matrix metalloproteinase-9 (Mmp-9) and its inhibitor Timp-1 were found to be important factors for developing hydrocephalus due to ECM environment alterations." (PMID 35047005, 2021). "In experimental hydrocephalus, adult rats had elevated MMP9 in the CSF after intraventricular kaolin injection while transgenic mice with TGF-β overexpression have reduced MMP9 mRNA and activity." (PMID 26846184, 2016). "Future investigations such as the addition of supplemental MMP-9 and/or IL-10, or the addition of pharmaceuticals counteracting IL-6 and IL-8, could help in understanding if the severity of hydrocephalus can be reversed, paused or mitigated." (PMID 33514409, 2021). "Some studies have shown increased MMP-9 disrupts the blood–brain barrier and could even be responsible for spontaneous hydrocephalus, while others have shown, in infants with PHH, MMP-9 can help them overcome symptoms of hydrocephalus." (PMID 33514409, 2021).
Hydrocephalus (continued). "Therefore, the interplay of IL-6, IL-8, IL-10, MMP-7 and MMP-9 is worth future investigations to improve our understanding of the molecular and cellular events driving hydrocephalus." (PMID 33514409, 2021). "We hypothesized that this abnormally activated MMP9 and possibly the eventual bleeding occurred secondarily to the inflammatory reaction in hydrocephalus." (PMID 31771992, 2019). "Similarly, the AUC of the combination of serum NLRP3, MMP‐9 and IFN‐γ for the diagnosis of hydrocephalus was 0.957, and the diagnostic efficacy of the combination of the three for hydrocephalus was higher than the diagnostic efficacy of NLRP3, MMP‐9 or IFN‐γ alone." (PMID 38643470, 2024). "Serum NLRP3, MMP‐9 and IFN‐γ levels were elevated in patients with post‐craniotomy intracranial infections/hydrocephalus." (PMID 38643470, 2024). "MMP9 is known to degrade collagen IV and collagen V, leading to tissue destruction and eventually blood–brain barrier disruption (Könnecke and Bechmann, 2013); therefore, it could exacerbate pathogenesis of the hydrocephalus by inducing bleeding and more inflammatory cell migration." (PMID 31771992, 2019). "MMP-9 and its specific inhibitor, TIMP-1, may contribute to the spontaneous development of hydrocephalus in this model by altering the ECM environment." (PMID 39908266, 2025). "Regarding the expression levels and diagnostic value of serum NLRP3, MMP‐9 and IFN‐γ in patients with hydrocephalus and intracranial infections after craniotomy, no studies have been reported." (PMID 38643470, 2024). "The area under the curve values of independent serum NLRP3, MMP‐9, IFN‐γ and their combination for diagnosing postoperative intracranial infection were 0.822, 0.722, 0.734 and 0.925, respectively, and for diagnosing hydrocephalus were 0.865, 0.828, 0.782 and 0.957, respectively." (PMID 38643470, 2024).
hypopharyngeal carcinoma (8 papers, 2013 to 2023). Carcinoma, predominantly squamous cell, arising from the epithelial cells of the hypopharynx. "In the present study, we demonstrated that elevated AEG-1 expression in hypopharyngeal cancer specimens was associated with increased expression of MMP-9." (PMID 27793010, 2016). "It was clearly indicated that AEG-1 expression markedly associated with MMP-9 expression in hypopharyngeal cancer." (PMID 27793010, 2016). "In order to investigate whether AEG-1 expression was associated with MMP-9 expression in hypopharyngeal cancer, we performed immunohistochemical staining of AEG-1, CD68 and MMP-9 (key regulator of tumor invasion) in serial sections." (PMID 27793010, 2016). "In hypopharyngeal carcinoma, the expression of MMP-9 is positively related to the angiogenetic process." (PMID 37445908, 2023). "The expression of MMP-2 and MMP-9 in hypopharyngeal carcinoma was significantly higher than that in pericarcinoma tissue, and it was enhanced with the increase of clinical stage." (PMID 31882379, 2021). "The results showed that the protein expression levels of MMP-2 and MMP-9 was consistent with the mRNA expression in hypopharyngeal carcinoma and pericarcinoma tissues." (PMID 31882379, 2021). "In hypopharyngeal cancer tissues, mRNA and protein levels of MMP-9 and MMP-2 are significantly upregulated compared to paracancerous tissues." (PMID 32961679, 2020). "Moreover, the expression levels are enhanced with the increased lymph node metastasis degree and tumor clinical stages, suggesting that MMP-2 and MMP-9 are involved in the occurrence and aggressiveness of hypopharyngeal cancer." (PMID 32961679, 2020). "Thus, MMP-2 and MMP-9 may be involved in the occurrence, development, invasion and metastasis of hypopharyngeal carcinoma through a variety of mechanisms." (PMID 31882379, 2021). "The anti-migratory efficacy of α-TOS is corroborated in hypopharynx carcinoma cells by decreasing the secretion of matrix metalloproteases 2 and 9 (MMP-2 and MMP-9) and inhibiting cell migration." (PMID 30235821, 2018). "In contrast with adjacent non-tumor samples, both AEG-1 and MMP-9 were more highly expressed in hypopharyngeal cancer." (PMID 27793010, 2016).
invasive ductal carcinoma (8 papers, 2009 to 2024). "Three (37.5%) out of the eight cases of invasive ductal carcinoma with adjacent in situ ductal component revealed positive MMP-9 expression in the in situ carcinoma lesions while the rest of the cases showed negative expression." (PMID 24993803, 2014). "In the current research, 37.5% of invasive ductal carcinomas with adjacent in situ component revealed positive MMP-9 expression in the in situ carcinoma lesions." (PMID 24993803, 2014). "Using immunohistochemistry, MMP-9, VEGF-C and the level of lymphatic microvessel density (LMVD) were analyzed in 106 cases of breast invasive ductal carcinoma and 20 cases of breast proliferative lesions." (PMID 26656588, 2015).
laryngeal squamous cell carcinoma (8 papers, 2016 to 2023). A squamous cell carcinoma that arises from the larynx. "It has been reported that LUCAT1 regulates MMP9 in Laryngeal squamous cell carcinoma cell lines, but its role in endometrial stromal cells remains to be studied." (PMID 35501804, 2022). "Here, we reported a novel regulatory pathway controlled by miR-744-3p, which enhanced expression of matrix metallopeptidase 9 (MMP-9) in laryngeal squamous cell carcinoma (LSCC)." (PMID 27533461, 2016). "Moreover, MMP-2 is more correlated with lymph node metastasis than MMP-9 in laryngeal squamous cell carcinoma." (PMID 32961679, 2020). "An investigation of the relationship between clinical characteristics and MMP9 expression in laryngeal squamous cell carcinoma found that MMP9 expression has found to be correlated with high histopathology grade, stage, metastatic potential, recurrence potential, and low survival." (PMID 26745629, 2016). "Another study showed that miR-139-3p is significantly downregulated in laryngeal squamous cell carcinoma and that its expression regulates several cancer-related genes, (e.g., RAB5A, ITGB1, FAK, PXN, VEGF, and MMP9)." (PMID 34576110, 2021). "This is the first study which separately analyzes peritumoral stroma and tumor core area in laryngeal squamous cell carcinoma in terms of CD45, CD11b, CD3, MMP-9 and COX-2 expression." (PMID 29492204, 2018). "In order to test this hypothesis, we assessed the relative importance of stromal versus tumoral inflammation for metastasis and overall survival in laryngeal squamous cell carcinoma applying five inflammatory markers: CD45, CD11b, CD3, MMP-9 and COX-2." (PMID 29492204, 2018).
osteopetrosis (8 papers, 2013 to 2025). Osteopetrosis, also known as marble bone disease, is a descriptive term that refers to a group of rare, heritable disorders of the skeleton characterized by increased bone density on radiographs. "In conclusion, we demonstrated that deletion of Ctsk and Mmp9 results in a severe osteopetrosis from impaired OC activation and function due to the loss of the compensatory functions of Ctsk and Mmp9 in osteoclasts." (PMID 36147479, 2022). "Collectively, the results indicated that DKO of Ctsk and Mmp9 caused a more severe osteopetrotic phenotype than Ctsk deletion, which causes mild osteopetrosis, while Mmp9 deletion had normal bone density, indicating that Ctsk could compensate for the loss of Mmp9 in Mmp9-/- mice." (PMID 36147479, 2022). "Cathepsin K knockout mice develop osteopetrosis because of the impaired matrix degradation; MMP-9 knockout mice show only transient disturbances in bone development." (PMID 23536866, 2013). "Moreover, during bone development, MMP9-null and MMP13-null mice exhibited expanded hypertrophic zones and osteopetrosis." (PMID 34976051, 2021).
pituitary tumor (8 papers, 2016 to 2025). A benign or malignant neoplasm affecting the pituitary gland. "Given the established association between pituitary tumors and elevated levels of MMP-9—and, to a lesser extent, MMP-2—there is potential for further research to develop radiolabels targeting these specific molecules." (PMID 41206839, 2025). "Other authors reported that in addition to the higher mRNA and protein expression levels of MMP-9 found in invasive pituitary tumors, these tumors also showed a decreased expression of TIMP-1." (PMID 31640258, 2019). "Moreover, the IL-6/JAK2/STAT3 pathway seems to be involved in the invasiveness of pituitary tumors by increasing the expression of MMP-9." (PMID 37958702, 2023). "The expression of matrix metalloproteinase-9 (MMP9) and vascular endothelial growth factor (VEGF) have been suggested to be closely related to pituitary tumor growth, invasion, and metastasis." (PMID 34564317, 2021). "In a study that included 54 pituitary tumors, it was reported that invasive pituitary tumors expressed increased levels of MMP-2 and MMP-9 mRNA and protein compared to non-invasive tumors." (PMID 31640258, 2019). "More importantly, their work highlights that increased serum levels of MMP-9 and decreased serum levels of TIMP-1 can be quantified in patients bearing invasive pituitary tumors." (PMID 31640258, 2019). "Also, the pituitary tumors of fetal alcohol exposed rats had elevated levels of oncogenes PTTG, FGF4 and MMP-9, which are known to be upregulated in the invasive prolactinoma and pituitary carcinoma." (PMID 29769550, 2018).
prostate adenocarcinoma (8 papers, 1994 to 2025). "Further, enhanced expression of SERPINB5 and MMP9 was associated with low survival in TCGA PRAD (The Cancer Genome Atlas Prostate Adenocarcinoma) patients." (PMID 34938177, 2021). "In a study on 100 patients with prostate adenocarcinoma, a strong functional interaction between FAK and MMP-9 has been shown and, consequently, enhanced the angiogenesis, invasion, and progression of prostate adenocarcinoma." (PMID 35335890, 2022). "Consistent with the observations shown in PC3 cells, high expression of active form of MMP9 was observed in prostatic adenocarcinoma tissue lysates." (PMID 24216994, 2013).
relapsing-remitting MS (8 papers, 2009 to 2024). "Experimental findings showed intrathecal synthesis of MMP-9 in MS and its increased levels in the cerebrospinal fluid and serum of relapsing-remitting MS patients compared with primary progressive and healthy control subjects." (PMID 37762899, 2023). "High serum MMP9 and low TIMP1 levels were associated with brain lesion formation in relapsing-remitting MS, and a decrease in the ratio was associated with interferon treatment." (PMID 28361271, 2018). "IFN-β is a promising treatment for MS and has been shown to repress MMP-7 and MMP-9 expression for patients with relapsing-remitting MS." (PMID 19267908, 2009). "Elevation of serum MMP9 has been identified in other neurodegenerative disease such as MS where it was found to be elevated in patients with relapsing-remitting MS and other inflammatory neurological diseases as compared to patients with non-inflammatory neurological diseases." (PMID 23185624, 2012). "The correlation between high levels of MMP-9 and the JCV reactivation in relapsing-remitting MS patients was another indicator for the role of MMP-9 in progressive MS." (PMID 32466129, 2020). "In other settings, e.g., in rIFNβ-1b-treated patients with relapsing-remitting multiple sclerosis, a negative correlation between sICAM-1 and MMP-9 has been described." (PMID 39337591, 2024). "MMP-9/TIMP-1 ratio may be viewed as a reliable marker and may be predictive of MRI activity in relapsing-remitting MS." (PMID 19490629, 2009).
retinal ischemia (8 papers, 2011 to 2025). A ischemic disease that involves the retina. "The increased levels of P-p38 and subsequent overexpression of MMP-9 detected during the current study were linked to retinal ischemia and/or wet age-related macular degeneration (wAMD)." (PMID 27617027, 2016). "In the case of transient intraocular pressure elevation, which leads to retinal ischemia, the MMPs are highly expressed in the trabecular meshwork, aqueous humor, retina, and optic nerve: there is evidence that MMP9 overexpression contributes to retinal damage in I/R injury." (PMID 35625734, 2022). "For instance, in models of retinal ischemia/reperfusion injury, RSV modulates the expression of matrix metalloproteinase-9 (MMP-9), inducible nitric oxide synthase (iNOS), and heme oxygenase-1 (HO-1), contributing to reduced vascular leakage and cell death." (PMID 40807437, 2025). "Treatment of the rats suffering from retinal ischemia with CJDHW inhibited apoptosis, increased antioxidative activity, downregulated MMP-9 and inhibited p38 MAPK." (PMID 27617027, 2016). "A recent study has shown that SAC was able to protect against retinal ischemia (not an uncommon cause of visual impairment) via inhibiting the upregulation of VEGF, MMP-9, and HIF-1α." (PMID 38279349, 2024). "Baicalein can also prevent retinal ischemia by reducing the levels of HIF-1α, VEGF, and MMP-9." (PMID 33149752, 2020).
spinal cord injury (8 papers, 2010 to 2025). Penetrating and non-penetrating injuries to the spinal cord resulting from traumatic external forces (e.g., WOUNDS, GUNSHOT; WHIPLASH INJURIES; etc.). "A recent study found that FA downregulates MMP-9 activity, particularly during the early stages of spinal cord injury (SCI), when MMP-9 is highly expressed." (PMID 40563423, 2025). "Upregulation of matrix metalloproteinases (MMPs), in particular MMP-2 and MMP-9 contributes to secondary pathogenesis of spinal cord injury (SCI) via promoting inflammation." (PMID 30234068, 2018). "Inhibiting the expression and activation of both metal matrix proteinase (MMP)-2 and MMP-9 after spinal cord injury (SCI) and the mRNA expressions of TNF-α, IL-1β, COX-2, and iNOS." (PMID 27951737, 2017). "Several members of the MMP family, including MMP-9 (gelatinase B) and MMP-12, have been implicated in early secondary pathogenesis after spinal cord injury (SCI)." (PMID 24788791, 2014). "Further mechanisms with relevance for neurologic disorders are the downregulation of matrix metalloproteinase-2 (MMP-2), MMP-9 and interleukin (IL-6) which, in an animal experiment of spinal cord injury (SCI), inversely correlated with the spinal water content, thus promoting recovery." (PMID 40731157, 2025). "Matrix metalloproteinase-9 (MMP-9) plays an important role in the acute periods of spinal cord injury (SCI), and its expression is related to the inflammation which could cause the disruption of the blood-spinal barrier (BBB)." (PMID 20862369, 2010).
systemic sclerosis (8 papers, 2005 to 2025). A chronic disorder, possibly autoimmune, marked by excessive production of collagen which results in hardening and thickening of body tissues. "We previously demonstrated the increased gelatinases (MMP2 and MMP9) activity in bleomycin-induced systemic sclerosis, and MMP9 was the main gelatinase in the lung tissues." (PMID 34912332, 2021). "Levels of MMP9, known to be increased and well correlated with skin scores in systemic sclerosis, were considerably increased in SScHDF cocultured with B cells." (PMID 24289101, 2013). "In this study, we investigated the expression of MMP-9 and its clinical significance in systemic sclerosis (SSc)." (PMID 15642145, 2005). "Overall, MMP dysregulation in systemic sclerosis reflects a complex imbalance between decreased MMP-1 and MMP-13 (profibrotic suppression) and increased MMP-9, MMP-14, and MMP-7 (proinflammatory activation)." (PMID 41226358, 2025). "Based on these results, we speculate that MMP-9, MMP-2, TIMP-2, and VEGF/sVEGFR-2 may play an important role in ischemic retinal degeneration or retinal reorganization in systemic sclerosis." (PMID 33218057, 2020).